ORMDL2 (ORMDL sphingolipid biosynthesis regulator 2)
Description:
Plays an essential role in the homeostatic regulation of sphingolipid de novo biosynthesis by modulating the activity of the serine palmitoyltransferase (SPT) in response to ceramide levels. When complexed to SPT, the binding of ceramides to its N-terminus stabilizes a conformation that block SPT substrate entry, hence preventing SPT catalytic activity. Through this mechanism, maintains ceramide levels at sufficient concentrations for the production of complex sphingolipids, but which prevents the accumulation of ceramides to levels that trigger apoptosis (By similarity).
Synonyms: HSPC160; MSTP095; adoplin-2; MST095
Tractability: Antibody: UniProt predicts a signal peptide or a membrane-spanning region. PROTAC: ubiquitination databases record sites on it; its protein half-life has been measured.
Gene: Protein-coding gene on chromosome 12 (55,818,041 to 55,821,879, forward strand). Ensembl gene ENSG00000123353.
Subcellular location: Endoplasmic reticulum membrane
Subcellular location (Human Protein Atlas): Endoplasmic reticulum
Pathways (Reactome):
Metabolism: Sphingolipid de novo biosynthesis
Gene Ontology:
Molecular function: protein binding
Biological process: ceramide metabolic process; negative regulation of ceramide biosynthetic process
Cellular component: endoplasmic reticulum; serine palmitoyltransferase complex; endoplasmic reticulum membrane; membrane
Genetic constraint (gnomAD): Loss-of-function variants: 11 observed, 14.21 expected, observed/expected ratio (o/e) 0.77, 90% interval 0.49 to 1.28. The upper end of that interval is the gene's LOEUF score, 1.28, which puts it in group 5 of 6, group 1 being the genes least tolerant of losing a copy. Missense variants: 160 observed, 202.07 expected, observed/expected ratio (o/e) 0.79, 90% interval 0.69 to 0.9. Synonymous variants: 73 observed, 81.36 expected, observed/expected ratio (o/e) 0.9, 90% interval 0.74 to 1.09.
Homologues: Orthologues: chimpanzee ORMDL2 (99% identical), macaque ORMDL2 (99% identical), dog ORMDL2 (97% identical), mouse Ormdl2 (97% identical), pig ORMDL2 (97% identical), rat Ormdl2 (97% identical), rabbit ORMDL2 (95% identical), guinea pig ORMDL2 (93% identical), tropical clawed frog ormdl2 (90% identical), zebrafish ormdl2 (87% identical), Drosophila melanogaster ORMDL (50% identical). Paralogues in human: ORMDL1 (83% identical), ORMDL3 (81% identical).
Diseases named in the same sentence as ORMDL2 in open-access papers:
ORMDL2 is named in the same sentence as 15 diseases in open-access papers, as found by Europe PMC text mining. Sharing a sentence is not in itself a finding about the gene and the disease. The quoted sentences say what the papers report.
asthma (2 papers, 2015 to 2020). "The human ORMDL1 and ORMDL2 genes, residing in other chromosomes than the ORMDL3 gene, might also be associated with asthma, as peripheral blood mononuclear cells from asthmatic patients exhibited increased expression of ORMDL1 and ORMDL2 genes." (PMID 33643282, 2020).
brain tumor (1 paper, 2025). "High ORMDL2 messenger (m)RNA was associated with poorer overall survival in all primary and recurrent brain tumor patients." (PMID 41049440, 2025). "However, the functional role of ORMDL2 in the context of human malignancies, particularly brain tumors still has remained elusive." (PMID 41049440, 2025).
breast carcinoma (1 paper, 2018). "In this study, breast cancer patients with high expression levels of ORMDL1 and ORMDL2 showed significantly better prognosis than those with low expression levels." (PMID 29731990, 2018). "We also found that breast cancer patients with low expression levels of ORMDL1 and ORMDL2 had a significantly worse prognosis than those with high expression levels." (PMID 29731990, 2018).
glioblastoma (1 paper, 2025). The most malignant astrocytic tumor (WHO grade IV). "Dysregulation of sphingolipid metabolism has been implicated in various cancers, yet the specific function of ORMDL2 in glioblastoma remains poorly defined." (PMID 41049440, 2025).
glioma (1 paper, 2025). A benign or malignant brain and spinal cord tumor that arises from glial cells (astrocytes, oligodendrocytes, ependymal cells). "The scRN-Seq analysis from the HPA revealed that ORMDL2 was highly expressed in TAMs and glioma stem-like cells (GSCs), two major contributors to immune evasion and therapeutic resistance in GBM." (PMID 41049440, 2025).
lung carcinoma (1 paper, 2025). "Until now, there is still a lack of evidence on the functions of ORMDL2 on lung cancer, and we proved that it is an oncogenesis gene, while lower levels of its autoantibody may predict an adverse prognosis." (PMID 39949782, 2025).
tumor (2 papers, 2025). "The specific expression of ORMDL2 in these immunosuppressive populations supports its candidacy as a modulator of tumor-associated immune evasion." (PMID 41049440, 2025). "The analysis provided insights into the expression pattern of ORMDL2 across transcriptionally distinct cell types within the tumor microenvironment (TME)." (PMID 41049440, 2025). "Single-cell RNA-sequencing data and the Human Protein Atlas showed ORMDL2 enrichment in tumor stromal cells." (PMID 41049440, 2025). "Remarkably, MetaCore enrichment highlighted “Antigen presentation by MHC class I cross-presentation” as the top-ranked pathway, implicating ORMDL2 in dendritic cell-mediated cross-priming and tumor antigen evasion." (PMID 41049440, 2025). "Among them, the expression of TIPRAP, WSCD1, TCP11L2, DPP4, CAB39 and PDPK1 were down-regulated, while PARP1, DEPDC1B, CKAP2, ORMDL2, MRPL44, POLD4 and TMEM187 were increased in tumor group." (PMID 39949782, 2025).
cancer (1 paper, 2025). A tumor composed of atypical neoplastic, often pleomorphic cells that invade other tissues. "Data from ATAC-Seq in the TCGA Pan-Cancer cohort further showed increased chromatin accessibility surrounding the ORMDL2 promoter, especially in mesenchymal-like samples." (PMID 41049440, 2025). "Transcriptomic analyses across The Cancer Genome Atlas (TCGA), and Chinese Glioma Genome Atlas (CGGA) revealed elevated ORMDL2 expression in GBM tissues which causes poor prognosis." (PMID 41049440, 2025). "To assess the therapeutic implications of ORMDL2 dysregulation in GBM, we conducted pharmacogenomic analyses was conducted using the Genomics of Drug Sensitivity in Cancer (GDSC) and Cancer Therapeutics Response Portal (CTRP) datasets." (PMID 41049440, 2025).
kidney diseases (1 paper, 2022). "Due to an abnormal sphingolipid metabolism could contribute to various pathologic processes, including kidney diseases, and activated mast cells were revealed according to the immune infiltration results, it is highly possible that ORMDL2 may an important role in IgAN." (PMID 35351150, 2022).
ORMDL2 also shares sentences with these, for which no sentence is quoted: anaphylaxis (1 paper); COVID-19 (1); Huntington disease (1); neurodegenerative disease (1); non-alcoholic fatty liver disease (1); Parkinson's (1).